SPINT2 (serine peptidase inhibitor, Kunitz type 2)
Diseases named in the same sentence as SPINT2 in open-access papers (continued):
Sharing a sentence is not in itself a finding about the gene and the disease.
cancer (40 papers, 2007 to 2026). A tumor composed of atypical neoplastic, often pleomorphic cells that invade other tissues. "Consistent with this conclusion is our analysis of the association of SPINT2 expression with survival for 39 different cancer types." (PMID 31737572, 2019). "In contrast, our current report utilized a loss-of-function analysis by homozygous knockout of the SPINT2 gene in cancer cells with sufficient HAI-2 expression." (PMID 29545930, 2018). "It should be noted that the major molecular mechanism underlying HAI-2 downregulation in cancer cells appears to be hypermethylation in the promoter region of the SPINT2 gene." (PMID 25268161, 2014). "SPINT2 (Serine Peptidase Inhibitor, Kunitz Type 2) is a gene known for its role in inhibiting serine proteases, and it has been studied primarily in the context of cancer and other diseases." (PMID 39466833, 2024). "Downregulation by hypermethylation of SPINT2 gene has been reported in several cancers, including hepatocellular carcinoma, RCC, melanoma, gastric carcinoma, and esophageal squamous cell carcinoma." (PMID 32290402, 2020). "SPINT2 protein level has been proposed as a marker of favorable prognosis by its suppressive actions on cancer cell growth, EMT, metastasis, and invasion." (PMID 31164631, 2019). "Previous studies suggested SPINT2 acts as an anticancer molecular and inhibits cancer development and progression." (PMID 31164631, 2019). "On the other hand, some cancers known to show SPINT2 promoter hypermethylation showed very low levels of SPINT2 mRNA." (PMID 29545930, 2018). "Human SPINT2 (HAI-2) is a physiological inhibitor of matrix cleaving proteases and decreased expression of SPINT2 has been linked to progression of several cancers." (PMID 23110343, 2012). "Given that c-Met inhibition induces senescence-like phenotypes in cancer cells, we hypothesized that SPINT2 promotes senescence through HGF/c-Met suppression." (PMID 40838961, 2025). "SPINT2 has been reported to be hypermethylated in many other cancers." (PMID 34381422, 2021). "What’s more, the SPINT2 gene is epigenetically silenced or downregulated in human cancers, altering the balance of Hepatocyte growth factor activation/inhibition ratio, which contributes to cancer development and progression." (PMID 32256213, 2020). "Interestingly, although SPINT2 is a putative suppressor, we demonstrate an increase in cancer ascites." (PMID 29499737, 2018). "On the other hand, HAI-2/SPINT2 may function as an HGFAC inhibitor to suppress HGF-MET signaling in cancer tissues." (PMID 30388869, 2018). "Moreover, the TCGA database also indicated significantly reduced SPINT2 mRNA levels in these cancer types." (PMID 29545930, 2018). "Finally, gene expression data from The Cancer Genome Atlas database (TCGA) revealed a strong correlation between the CDKN1A and SPINT2 expression levels in healthy samples, and a weak correlation in cancer samples in which SPINT2 is frequently mutated." (PMID 34962618, 2022). "Therefore, SPINT2/HAI‐2 may participate in the functional and morphological abnormalities of the microenvironment niche and cancer progression, possibly contributing to chemotherapy resistance." (PMID 30484958, 2019). "Bikunin, TFPI-2 and SPINT2 are Kunitz proteins with anti-cancer effects, and as potent protease inhibitors, the EgKI proteins may also exhibit similar properties which can be exploited in cancer therapy." (PMID 26645974, 2015). "SPINT2 gene expression was down-regulated, altering dysregulation of the HGF/MET signaling pathway, which contributes to cancer development and progression." (PMID 32256213, 2020). "The serine peptidase inhibitor Kunitz type 2 (SPINT2), a Caco-2 line-specific EV protein, inhibits HGF and suppresses the progression of various types of cancer." (PMID 32916986, 2020).
cancer (continued). "The qPCR studies identified five mRNA (CA11, MEDAG, LAMA4, SPINT2, NANOG) and six miRNA (let-7b, miR23b, miR29a, miR30d, miR205, miR720) that were significantly differentially expressed between cancer ascites and peritoneal fluids." (PMID 29499737, 2018). "Because the increased ratio of ST14/Prss14 to its inhibitor SPINT1 was observed in some carcinomas, we examined the ratio of ST14/Prss14 to SPINT1 and SPINT2." (PMID 27167193, 2016). "The comparison of the individual relative densities of cancer cells in both cell line models between AA and CAU women revealed altered expression in 5 of the 14 potential biomarkers (Atp1b1, CARD 10, KLF4, Spint2, and Acly)." (PMID 17472751, 2007). "Since cellular senescence is involved in aging, tissue degeneration, and cancer, modulating DNMT1, SPINT2, and c-Met signaling could provide novel therapeutic opportunities." (PMID 40838961, 2025). "Although DDX19B and PANK2 (but not NEMP1 and UBALD1) were synergistically expressed with SPINT2 in PTC, there are no reports relating these genes with SPINT2 in any form of cancer." (PMID 32887258, 2020). "SPINT2, the identified GMR of the profiled PTC, was previously reported by several groups to be involved in the development and progression of a wide diversity of forms of cancer." (PMID 32887258, 2020). "The two mRNA markers SPINT2 and NANOG that are upregulated in cancer ascites relative to peritoneal fluids may have potential as diagnostic biomarkers." (PMID 29499737, 2018). "The ratio of ST14/Prss14 to SPINT1, ratio(I), and that of ST14/Prss14 to SPINT2, ratio(II), showed no big difference among the cancer stages." (PMID 27167193, 2016). "What effect the overexpression of an otherwise stably expressed but not regulated gene in PTC (SPINT2) may have on cancer cells?" (PMID 32887258, 2020). "While significant alteration of the expression of SPINT2 would have lethal impact on the cancer cells, due to the very low GCH in NOR (GCHSPINT2(NOR) = 1.93), it might have very little consequences on the normal cells." (PMID 32887258, 2020). "What are the mechanisms by which experimental alteration of SPINT2 expression might selectively kill the cancer cells but not the normal ones?" (PMID 32887258, 2020). "Thus, SPINT2/HAI‐2 may contribute to functional and morphological abnormalities of the microenvironment niche and to stem/progenitor cancer cell progression." (PMID 30484958, 2019). "The substantial increase in the expression synergism of SPINT2 with apoptosis genes in the cancer nodule with respect to the surrounding normal tissue (NOR) suggests that SPINT2 experimental overexpression may force the PTC cells into apoptosis with a negligible effect on the NOR cells." (PMID 32887258, 2020). "Because the CYP2A6 locus in the 19q13 region is separated from the SPINT2 and ACTN4 loci by many genes, CYP2A6 amplification in human cancer has not been shown." (PMID 27902773, 2016).
infection (4 papers, 2020 to 2023). The state of being infected such as from the introduction of a foreign agent such as serum, vaccine, antigenic substance or organism. "Our findings clearly show that SPINT2 regulates SARS-CoV-2 viral infection through the inhibition of TMPRSS2, since a drug induced inhibition of TMPRSS2 abrogates the infection-promoting effect of SPINT2." (PMID 34181691, 2021). "Relative concentrations of the attachment receptor, ACE2, MASPs, their endogenous inhibitors (the Kunitz-type transmembrane inhibitors, HAI-1/SPINT1 and HAI-2/SPINT2, as well as major circulating serpins) would determine the infection rate of host cells." (PMID 33268377, 2021).
neurodegenerative disease (1 paper, 2023). A disorder of the central nervous system characterized by gradual and progressive loss of neural tissue and neurologic function. "Yet another identified indirect interaction between COMT and SPINT2 was mediated via APP, protein associated with occurrence of neurodegenerative diseases such as Alzheimer disease." (PMID 36690660, 2023).
SPINT2 also shares sentences with these, for which no sentence is quoted: renal cell carcinoma (6 papers); colon carcinoma (5); esophageal squamous cell carcinoma (3); haematological neoplasms (3); leukemia (3); non-small cell lung carcinoma (3); bladder cancer (2); cervical carcinoma (2); colorectal cancer (2); lung adenocarcinoma (2); myeloma (2); airway hyperresponsiveness (1); bone metastasis (1); Burkitt lymphoma (1); chordoma (1); Cirrhosis (1); colon adenocarcinoma (1); esophageal carcinoma (1); Ewing sarcoma (1); Failure to thrive (1); insulinomas (1); intestinal disorder (1); liver cancer (1); lymphoma (1); malaria (1); malignant brain tumors (1); meningioma (1); metastatic melanoma (1); metastatic tumours (1); Moyamoya disease (1).
A further 10 diseases each share a sentence with SPINT2 in 1 paper.